TSPO (translocator protein)
Diseases named in the same sentence as TSPO in open-access papers (continued):
Sharing a sentence is not in itself a finding about the gene and the disease.
cancer (continued). "The results showed a strong correlation between TSPO expression and stemness features across various cancer cells." (PMID 40936684, 2025). "TSPO protein expression has been reported to correlate positively with disease progression in some cancers, including oral cancer." (PMID 40961028, 2025). "Overexpression of TSPO has been observed in numerous malignancies, suggesting a potential role in cancer pathogenesis and progression." (PMID 40550494, 2025). "IHC staining showed that malignant tumors with high TSPO expression had significantly higher AKR1C1 and FTH1 expression levels." (PMID 40842566, 2025). "Future research should continue to explore the multifaceted role of TSPO in cancer and its potential as a therapeutic target." (PMID 40550494, 2025). "Through a comprehensive assessment of TSPO levels in CRC patients, we aim to elucidate its potential role in cancer progression and evaluate its viability as a diagnostic and prognostic tool." (PMID 40550494, 2025). "The results were expected to shift the trend in the future from focusing only on TSPO-targeted therapy but also on developing TSPO-targeted hybrid probes for image-guided surgery of cancer." (PMID 38585455, 2024). "As with TSPO, a direct association of the level of VDAC and the degree of cancer aggressiveness is known." (PMID 38675106, 2024). "In conclusion, TSPO was an appealing molecular target for various human diseases, including neurodegenerative diseases, inflammation, and cancer." (PMID 38585455, 2024). "An abundance of TSPO in cancer cells is used in photodynamic therapy after recruitment of photo-sensitive TSPO ligands." (PMID 38675106, 2024). "The study aimed to improve the specificity and efficacy of BNCT by selectively targeting cancer cells that overexpress TSPO." (PMID 38961887, 2024). "The levels of TSPO mRNA, as well as the protein itself, in cancer cells are usually much higher than in normal cells, indicating that transcription of TSPO increases in hyperplastic tissue." (PMID 38675106, 2024). "According to a previous study, the expression of TSPO was upregulated in cancer cells, which corresponds to an aggressive phenotype and/or poor prognosis." (PMID 38585455, 2024). "Previously, both TSPO over- and underexpression have been reported in different types of cancers compared to their healthy counterpart tissues." (PMID 38162485, 2023). "Previously, TSPO expression in HNSCC had only been studied in a small cohort of patients with carcinomas of the oral cavity." (PMID 38162485, 2023). "Herein, we review the current evidence for the role of TSPO and its ligands in the development of chronic pain, including neuropathic pain, cancer pain, and inflammatory pain." (PMID 36071748, 2022). "Previous clinical research revealed that TSPO expression levels are elevated in various cancers including glioma, and increased TSPO expression was positively correlated with poor prognosis, as observed in our present study." (PMID 35285415, 2022). "Cumulative findings have clarified that TSPO plays a vital role in alleviating the initiation and maintenance of chronic pain, including neuropathic pain, inflammatory pain, and cancer pain." (PMID 36071748, 2022). "TSPO is involved in various cellular functions that are relevant to cigarette smoking, such as oxidative stress, programmed cell death, inflammation, and cancer." (PMID 34063262, 2021). "PLGA NPs have also been conjugated to synthetic ligands of the translocator protein 18 kDa (TSPO), a mitochondrial protein that is overexpressed in many cancer types." (PMID 34683830, 2021). "TSPO levels were found to be elevated in cancer cell lines and numerous cancers suggesting a role for TSPO in cell proliferation and carcinogenesis." (PMID 33433698, 2021). "While some level of TSPO and VDAC1 binding is needed to regulate the mitophagy pathway, overexpression of TSPO led to increased binding to VDAC1 which resulted in an accumulation of dysfunctional mitochondria in cancer cells." (PMID 34359907, 2021).
cancer (continued). "Increased TSPO levels in cancer are due to gene amplification; Sp1, Sp3, and Sp4 transcription factor regulation of constitutive TSPO expression; and epigenetic modifications of the proximal promoter and first intron." (PMID 33433698, 2021). "TSPO is overexpressed in many cancer types and its level correlates with tumor malignancy, as well as cancer progression." (PMID 34805097, 2021). "TSPO expression is highly upregulated in cancer and at the sites of neuroinflammation processes in cerebral ischemia, Alzheimer’s, Parkinson’s, and Huntington’s diseases, and multiple sclerosis." (PMID 33652554, 2021). "Many cancer types exhibit increased TSPO expression, which has been related to an aggressive phenotype and/or poor prognosis." (PMID 33340054, 2021). "In recent years, TSPO is increasingly appreciated as a potential novel therapeutic target in cancer." (PMID 33066460, 2020). "The aim of this review is to summarize the current literature on TSPO with respect to its role both in diagnostics and especially with regard to the critical hallmarks of cancer postulated by Hanahan and Weinberg." (PMID 33066460, 2020). "Several studies have found a strong correlation between TSPO expression levels and aggressive cancer phenotypes." (PMID 33066460, 2020). "Here, using IHC of healthy and cancer tissue arrays and quantitative analysis, we demonstrate that the levels of TSPO were 10-fold higher in brains from patients with GBM than in healthy tissue." (PMID 31661894, 2019). "TSPO is involved in several functions such as programmed cell death, inflammation, cancer, oxidative stress, and mitochondrial membrane potential regulation." (PMID 31295884, 2019). "In various types of cancers, including large bowel, brain, mammary gland, ovary, and liver, the expression of TSPO is increased." (PMID 30248940, 2018). "In the present work, TSPO ligand–dextran conjugate NGs, based on biodegradable dextran, were used as a carrier for the efficient delivery of pro-apoptotic TSPO ligands into cancer cells overexpressing TSPO." (PMID 29641449, 2018). "The 18-kDa translocator protein (TSPO), which is located mainly in the outer membrane of mitochondria, is a well-established biomarker of brain injury and cancer because it is excessively expressed in such lesions." (PMID 29342117, 2018). "It is known that knockdown of the mitochondrial 18 kDa translocator protein (TSPO) as well as TSPO ligands modulate various functions, including functions related to cancer." (PMID 28387723, 2017). "TSPO is thus a suitable biomarker candidate for a number of inflammatory diseases and cancer, and it has also been explored as a prognostic marker and a therapeutic target." (PMID 26194010, 2016). "TSPO is involved in several pathophysiological processes, such as steroidogenesis, immunomodulation, apoptosis, brain injury, neurodegeneration, and cancer." (PMID 27322261, 2016). "Here, we investigated the TSPO radioligand [18F]DPA-714 for positron emission tomography (PET) imaging of cancer and inflammation." (PMID 26194010, 2016). "The present results show that even though TSPO is evolutionary conserved and its expression is boosted in inflammation and cancer in both mice and rats, the in vivo imaging performance of [18F]DPA-714 is clearly species dependent." (PMID 26194010, 2016). "In the present study, we investigate the biodistribution of [18F]DPA-714 and its ability to highlight TSPO expression in different mouse and rat models of cancer and peripheral inflammation." (PMID 26194010, 2016). "In the TSPO-rich cancer imaging study, the PET image of [18F]CB251 visually reflected the ex vivo biodistribution of 18F uptake in mice." (PMID 26853260, 2016). "In mammals, TSPO is expressed in almost every tissue type, but is particularly enriched in steroidogenic and some cancer cells." (PMID 26441945, 2015).
cancer (continued). "TSPO expression dysregulation has been correlated to several diseases, including cancer, neuronal damage, neurodegeneration, and inflammation." (PMID 26441945, 2015). "TSPO is highly expressed in various cancer cell types, including colon, brain, breast, ovary and liver cancer, and its expression is particularly high in organs involved in steroidogenesis." (PMID 25663907, 2015). "TSPO expression is dysregulated during disease pathologies involving changes in tissue energy demands such as cancer, and is up-regulated in activated macrophages during the inflammatory response." (PMID 24260329, 2013). "highlighted the complexity of TSPO's role across different cancer types." (PMID 40550494, 2025). "This alignment suggests that TSPO could be an effective target for novel therapeutic strategies and image‐guided surgeries, offering a promising direction for future cancer treatments." (PMID 40550494, 2025). "For that reason, TSPO has attracted attention as a possible molecular marker for cancer." (PMID 40961028, 2025). "Also, TSPO was shown to be present in various human cancer cells, potentially reducing the specificity of TSPO-imaging for M2 macrophage detection." (PMID 40725764, 2025). "TSPO significantly impacts cellular functions crucial for cancer progression; its interaction with voltage‐dependent anion channels influences mitochondrial function and cellular metabolism, which are essential for cancer cell survival and proliferation." (PMID 40550494, 2025). "The relevance of TSPO to cancer is very high, although the reason for this is incomprehensible." (PMID 38675106, 2024). "According to a previous study, TSPO played a major role in apoptosis and chemosensitization in cancer cells, making it a suitable target for drug development aimed at developing new therapeutic strategies and a biological marker for cancer imaging." (PMID 38585455, 2024). "During cancer cell proliferation, TSPO accumulated in the nucleus." (PMID 38585455, 2024). "Therefore, this review aims to highlight recent results on the involvement of TSPO in various types of cancers and discuss its prospect as a novel targeted receptor in cancer surgery." (PMID 38585455, 2024). "Overall, the data indicate that while TSPO may play a role in the immune landscape of some cancers, its potential immunomodulatory role may be less important in the context of HNSCC." (PMID 38162485, 2023). "High translocator protein (TSPO) levels have been associated with poor survival in cancer, but the role of TSPO has not been extensively evaluated in HNSCC." (PMID 38162485, 2023). "TSPO is overexpressed in cancer cells, making it a potential target for cancer therapy." (PMID 38813501, 2023). "In sum, we hypothesized that compared to matched healthy controls, cancer survivors would yield higher microglial activation measured by TSPO expression, and lower fractional anisotropy measured by DTI." (PMID 37751068, 2023). "The mitochondrial translocator protein (TSPO) has been found to play a key role in several cellular processes, such as cell life/death, and TSPO ligands have been demonstrated to be valid candidates for the treatment of several diseases, including cancer." (PMID 36985576, 2023). "Therefore, RIPK1, like COX-1/2 and TSPO, is considered as a target enzyme for treatment against cancers and other inflammation diseases in multiple tissues." (PMID 35290562, 2022). "TSPO, the proposedtether in the cancer study, is also universally conserved." (PMID 36338149, 2022). "Imaging of TSPO in cancer might hence be a useful tool to establish prognosis and indicate response to treatment strategies." (PMID 33340054, 2021). "Many malignant tumours have increased TSPO expression, which has been related to a poor prognosis." (PMID 33340054, 2021). "Imaging of TSPO in cancer could therefore be a useful tool in treatment planning and/or for the development of new TSPO-targeting drugs." (PMID 33340054, 2021).
cancer (continued). "Likewise, TSPO was predicted to be involved in neuroinflammatory, inflammatory, psychiatric, and metabolic diseases as well as cancer." (PMID 34212002, 2021). "This article hypothesizes that TSPO in GBM relates to many of the hallmarks of cancer, published first by Hanahan and Weinberg in a groundbreaking, conceptual article in 2000." (PMID 33066460, 2020). "TSPO has been shown to be overexpressed in a variety of cancers." (PMID 31661894, 2019). "The prognosis of some cancers also correlates negatively with the expression of TSPO." (PMID 30044440, 2018). "Moreover, selective TSPO ligands have been widely investigated for diagnostic purposes and explored to target drug delivery systems directed to cancer cells overexpressing TSPO." (PMID 29641449, 2018). "Recently, TSPO gene has been suggested as a novel target for cancer chemotherapy." (PMID 29318061, 2017). "Moreover, TSPO is overexpressed by macrophages at inflammatory and cancer sites, as well as by neutrophils that migrate into the liver after injection with cycloheximide or into the lungs after systemic injection of lipopolysaccharides (LPS)." (PMID 29163156, 2017). "Therefore, in this study, MTX was selected to achieve two TSPO ligand-MTX conjugates (TSPO ligand α-MTX and TSPO ligand γ-MTX), potentially useful for the treatment of TSPO-rich cancers, including brain tumors." (PMID 27322261, 2016). "Several studies have reported changes in TSPO expression and potential role in various cancers." (PMID 27608010, 2016). "Thus, numerous studies have proposed TSPO as a promising target for novel therapeutic agents, particularly for the treatment of cancer." (PMID 25663907, 2015). "Activation of the cancer cell death machinery through the mitochondrial membrane permeabilization has been obtained so far also by the use of drugs targeting the mitochondrial translocator protein (TSPO)." (PMID 24756113, 2014). "Taken together, these results suggest that TSPO/MDM2 dual-target ligands could represent a new attractive multi-modal opportunity for anti-cancer strategy in GBM." (PMID 24756113, 2014). "Moreover, the basis of pathological upregulation of TSPO as seen in cancer cells remains to be established." (PMID 24040265, 2013). "Furthermore, TSPO is also dysregulated during disease pathologies such as cancer which involve changes in cellular energy demands." (PMID 24260329, 2013). "The 18 kDa TSPO protein is a polytopic mitochondrial outer membrane protein involved in a wide range of physiological functions and pathologies, including neurodegeneration and cancer." (PMID 20541505, 2010). "Additionally, targeting TSPO with inhibitors might slow cancer progression by reducing cell proliferation and promoting apoptosis." (PMID 40550494, 2025). "Our analysis also predicted that TSPOAP1 and TSPO strongly regulate sirtuin signalling, which may contribute to sirtuins mediated control and regulation of metabolism, oxidative stress, and DNA damage in inflammation and cancer." (PMID 34212002, 2021). "However, even though final conclusions cannot be drawn from our study, our results with FaDu cells indicate that the Am might affect the uptake of TSPO tracers, also in cancer." (PMID 33340054, 2021). "TSPO over-expression in cancer might thus be required to support these functions." (PMID 31661894, 2019). "Moreover, increased TSPO expression could be correlated with a more aggressive cancer cell phenotype." (PMID 31661894, 2019). "In addition, some investigators believe that TSPO plays a key role in cancer cell growth." (PMID 30248940, 2018). "Thus, our study revealed one more type of cancer presenting TSPO dysregulation." (PMID 27608010, 2016). "Additionally, TSPO is regarded as a potential prognostic factor in cancer." (PMID 25663907, 2015). "Due to the previously suggested immunomodulatory role of TSPO in neuroinflammation, we studied the correlation of TSPO expression with the abundance of immune cell types in HNSCC and other cancer types." (PMID 38162485, 2023).
cancer (continued). "The first study hypothesised that nmMCS might catalyse MRR in the context of pro-survivalpathways in cancer cells, via the mediation of cholesterol, reactive oxygen species andcalcium.The authors focused on the outer membrane translocator protein (TSPO) as a key candidate fortethering." (PMID 36338149, 2022). "Therefore, establishing the mechanisms that induce proliferation and restoration of the epithelial tissue and regulate Tspo mRNA transcription may help in understanding the role that the TSPO protein plays in various cancers and may allow for it to be exploited as a prognostic marker in cancers." (PMID 30044440, 2018). "It was evaluated to detect neuroinflammation as well as TSPO-rich cancer in animal models as a favorable PET radiotracer and has shown specific and reasonable uptake in abnormal TSPO expression lesions." (PMID 29342117, 2018). "Recently, we identified new reversible compounds dual-targeting MDM2 and TSPO, two proteins that are both up-regulated in GBM so contributing to cancer cell resistance to physiological apoptosis." (PMID 26761214, 2016). "Recently, we have characterized TSPO/MDM2 dual-target ligands and demonstrated that these agents present an attractive multi-modal anti-cancer activity in GBM cells." (PMID 26761214, 2016). "To investigate the relationship between TSPO and ferroptosis in MPNST, we used RT-qPCR to detect the differential mRNA expression levels of two classic ferroptosis biomarkers, AKR1C1 and FTH1, in tissues from patients with benign and malignant tumors." (PMID 40842566, 2025). "Non-malignant tissue also expressed higher TSPO levels than carcinomas regardless of N or T classification or overall staging (all p < 0.001)." (PMID 38162485, 2023). "This review provides a critical overview of how TSPO could regulate several aspects of tumorigenesis in GBM, particularly in the context of the hallmarks of cancer proposed by Hanahan and Weinberg in 2011." (PMID 33066460, 2020). "In addition, affinity for TSPO (IC50 = 18.64 nM), cellular uptake (ca. 2 times greater than that of oxaliplatin in LoVo cancer cells, after 24 h treatment), and perturbation of cell cycle progression were investigated." (PMID 27347942, 2016). "Moreover, a number of these agents induce MPT targeting MPTP components that are selectively up-regulated in cancer cells, such as the TSPO and ANT proteins, thus reinforcing the cancer selective action of the therapy." (PMID 19196452, 2009). "Moreover, the use of TSPO as a salivary biomarker in potentially malignant disorders has not been reported yet." (PMID 40961028, 2025). "The role of the overexpressed TSPO in cancer is not clear although it may be related to the cholesterol transport activity of the protein." (PMID 31661894, 2019). "Gene amplification does not appear to be sufficient to explain the increased TSPO in cancer cells." (PMID 27077069, 2016).